SMYD2 (SET and MYND domain containing 2)
Diseases named in the same sentence as SMYD2 in open-access papers (continued):
Sharing a sentence is not in itself a finding about the gene and the disease.
cancer (continued). "Given the extensive involvement of SMYD2 in various cancers and its demonstrated therapeutic value in preclinical studies, the discovery of this novel allosteric site opens exciting possibilities for cancer drug development." (PMID 39677743, 2024). "Although emerging evidence supports the association of SMYD2 in the progression of cancers, but its definitive effect is not yet clear." (PMID 37971632, 2023). "For cancers in which SMYD2 is overexpressed, LLY-507 has shown antiproliferative activity." (PMID 37513898, 2023). "Furthermore, we used to study the correlation between the cancer pathological stages (stages I–V) and SMYD2 expression." (PMID 37971632, 2023). "Therefore, it has been evidenced that SMYD2 is an onco-related protein that can affect the function of cancer suppressor proteins." (PMID 37971632, 2023). "We found higher SMYD2 mRNA expression in all studied cancers." (PMID 37971632, 2023). "Additionally, in vivo and in vitro research is necessary to clarify SMYD2 as a potential biomarker for cancer." (PMID 37971632, 2023). "Collectivelly, we identified that SMYD2 was not only potential biomarker but also may be of promising therapeutic target for multiple cancers." (PMID 37971632, 2023). "Hence, we discovered a possible correlation between SMYD2 expression and methylation in a range of cancers." (PMID 37971632, 2023). "The pan-cancer analysis provides a potential mechanism that suggested the expression of SMYD2 might modulate tumors." (PMID 37971632, 2023). "The expression of SMYD2 varied more than six orders of magnitude in maximum cancer types." (PMID 37971632, 2023). "Our in vitro data showed that knockdown of SMYD2 decreased the expression of EMT-related genes, indicating that loss of SMYD2 may decrease the efficiency of cancer cell penetration from vessels to the liver." (PMID 37121971, 2023). "Therefore, in the present study, we executed a multi-omics analysis to better understand the role of SMYD2 in diverse cancers." (PMID 37971632, 2023). "In addition, we also examined the correlation between SMYD2 gene expression and immunocyte infiltration in multiple cancer types." (PMID 37971632, 2023). "The genetic alteration analysis of SMYD2 in several cancers was performed using cBioPortal." (PMID 37971632, 2023). "The regulatory effect of SMYD2 on diverse cancers is different, though further experimental studies are desired to understand the complete molecular analysis of SMYD2 to identify its more effective biomarker role for cancer." (PMID 37971632, 2023). "Thus, diverse methylated substrates mediate the function of Smyd2 in diseases, such as cardiovascular disease and cancer; however, little is known about its function in other diseases." (PMID 35297562, 2022). "Considering the importance of the pleotropic impacts of SMYD2 on cancer biology and the hypothesis that targeting SMYD2 may impair the PC recurrence, the current study reports the novel role of SMYD2 in mCRPC pathogenesis." (PMID 35884603, 2022). "However, a recent study using small molecule inhibitors and CRISPR/Cas9 technology targeting SMYD2 in hundreds cancer cell lines questioned the functional role of SMYD2 in tumor cell proliferation." (PMID 35022391, 2022). "Several inhibitors for SMYD2 have been reported for the beneficial effects of suppressing cancer." (PMID 35668081, 2022). "As an oncogene, SMYD2 has been investigated in numerous types of cancer." (PMID 33935284, 2021). "BAY-598 (500 mg/kg, q.d.)significantly reduced tumor growth in an in vivo esophageal xenograft model only combined with doxorubicin, suggesting the potential for limitations in the application of SMYD2 inhibitors to specific anticancer drugs in response to certain types of cancer." (PMID 34201935, 2021). "SMYD2, which has less limited substrate specificity, is attracting attention as an anticancer target molecule because of the negative correlation between expression levels and patient survival rates in various cancer types." (PMID 34201935, 2021).
cancer (continued). "SMYD2 functions as a lysine methyltransferase and has been previously shown to promote proliferation, epithelial‐mesenchymal transition, and invasion of a variety of cancer cell types." (PMID 33459509, 2021). "In this review, we overview what is currently known about SMYD2 in cancer and embryogenesis and hypothesize new areas for studying SMYD2 in embryogenesis based on preliminary data and analysis of what is currently known." (PMID 32408548, 2020). "Targeting the SMYD2-WNT-β-catenin pathway in HSCs may provide a successful approach for future cancer therapies." (PMID 32408548, 2020). "A study showed that multiple sites in the CRU region of AHNAK2 could be methylated by SMYD2, thus participating in the regulation of cell adhesion, cancer cell migration, and invasion." (PMID 32904605, 2020). "However, SMYD2 has received the bulk of its research attention because of its overexpression in several cancers and its interactions with known oncogenes." (PMID 32408548, 2020). "These compounds are promising for the treatment of a wide range of cancers and may also prove to be useful for further investigation of SMYD2 function." (PMID 32408548, 2020). "However, the bulk of research involving SMYD2 has centered on its role in carcinogenesis because of its detected overexpression in a wide range of human cancers." (PMID 32408548, 2020). "Since aberrant SMYD2 expression and its dysfunction are often closely related to multiple diseases, SMYD2 is a promising candidate for the treatment of these diseases, such as cardiovascular disease and cancer." (PMID 31370883, 2019). "However, a recently published study offered a different conclusion; this study used CRISPR/Cas9 to genetically ablate SMYD2, and the results indicated that SMYD2 activity is dispensable for autonomous cancer cell proliferation." (PMID 31370883, 2019). "Thus, the substrates of SMYD2 are diverse, and methylated substrates mediated the function of SMYD2 on diseases, such as cardiovascular disease and cancer." (PMID 31370883, 2019). "SMYD2/miR-125b-targeted therapies may be considered a novel strategy for reversing the resistance of cancer cells to chemotherapy treatment." (PMID 31754403, 2019). "SMYD2 overexpression has been observed in all the types of tumors investigated, and knockdown or inhibition of SMYD2 suppresses tumor cell growth by methylating different substrates in different cancers." (PMID 31370883, 2019). "The role of SMYD2 in cardiovascular disease and cancer has been extensively investigated, but its function in other diseases remains largely unknown." (PMID 31370883, 2019). "Thus, 5 compounds representing 4 distinct pharmacophore series of SMYD2 inhibitors are now available for testing the dependence of cancer lines on SMYD2 activity." (PMID 29856759, 2018). "Furthermore, after treatment with a SMYD2 inhibitor, significant reduction of nuclear β-catenin and subsequent induction of cancer cell death are observed." (PMID 28915556, 2017). "Furthermore, treatment of cancer cells with the SMYD2-specific inhibitor also abolished the nuclear localization of the β-catenin." (PMID 28915556, 2017). "Moreover, knockdown of SMYD2 attenuated growth of several epithelial and mesenchyme derived cancer lines." (PMID 28187429, 2017). "Knockdown of SMYD2 attenuates the nuclear localization of β-catenin protein in human cancer cells." (PMID 28915556, 2017). "However, when SMYD2 is transactivated in cancer cells, stabilized β-catenin is methylated by SMYD2, binds to FOXM1, enters into the nucleus with FOXM1, and then activates downstream genes in the Wnt/β-catenin/TCF pathway." (PMID 28915556, 2017). "However, genetic evidence for a role of Smyd2 in other cancers or in mouse development was missing to date." (PMID 27655694, 2016).
cancer (continued). "Together, these results suggest that MAPKAPK3 could be a cancer-relevant cytoplasmic target of SMYD2." (PMID 26988419, 2016). "Oncomine analysis of primary tumors from 14 different cancer types showed that SMYD2 is not frequently mutated in cancer (left)." (PMID 25825497, 2015). "Therefore, SMYD2 overexpression is a significant factor in the growth of various cancers." (PMID 39482529, 2024). "Thus, designing a therapeutic drug that selectively inhibits SMYD2 function in cancer cells may require the identification of targets in only a subset of SMYD2-expressing cells." (PMID 36838987, 2023). "Thus, SMYD2 can be used for the diagnosis of several cancers." (PMID 37971632, 2023). "Furthermore, the oncogenic role of SMYD2 has been unveiled in a range of cancers." (PMID 35668081, 2022). "Next, we evaluated whether SMYD2 expression had an effect on the survival rates of cancer patients." (PMID 33935284, 2021). "In addition to cardiovascular diseases, the role of SMYD2 in cancer has received broader attention." (PMID 31370883, 2019). "The number of viable cells was significantly decreased with the inhibitor treatment in a dose-dependent manner, implying that an inhibitor(s) targeting SMYD2 could suppress SMYD2-mediated β-catenin methylation, reduce β-catenin nuclear translocation, and subsequently induce cancer cell death." (PMID 28915556, 2017). "Knockdown of SMYD2 abolished β-catenin methylation and nuclear localization of β-catenin through the loss of the interaction with FOXM1, resulted in the downregulation of the Wnt/β-catenin/TCF downstream genes such as c-myc and cyclin D, and subsequently induced cancer cell death." (PMID 28915556, 2017). "Since it is known that the majority of SMYD2 protein is located in the cytoplasm, we hypothesized that methylation of a lysine residue in β-catenin might affect its subcellular localization in cancer cells as we reported examples in our review and in turn, regulate the Wnt signaling pathway." (PMID 28915556, 2017). "By developing drugs that specifically inhibit SMYD2 and SMYD3, researchers hope to provide new, more effective treatments for cancer patients." (PMID 39482529, 2024). "Therefore, SMYD2 expression could be utilized as a prognostic marker for various cancer types." (PMID 39482529, 2024). "In particular, research and the development of specific inhibitors for SMYD2 and SMYD3 have demonstrated the potential of targeting these proteins to inhibit the growth and metastasis of various cancers." (PMID 39482529, 2024). "The number of studies on SMYD4 and SMYD5 in the field of cancer has increased, although relatively few reports have compared SMYD4 and SMYD5 to SMYD2 and SMYD3." (PMID 39482529, 2024). "A high level of SMYD2 in CESC (HR 2.3, p = 0.00045) and a lower level of SMYD2 in KIRC (HR 0.49, p = 6E-06) were significantly correlated with the OS of cancer patients." (PMID 37971632, 2023). "Recruitment of the PARP1 enzyme to DNA damage sites is regulated by SMYD2 methylation at K528, a methyl mark that enhances PARP1 activity in cancer cells." (PMID 37894343, 2023). "Meanwhile, SMYD2 and GAPDHP1 expression levels in cancer tissues were higher than in paracancerous tissues." (PMID 35498536, 2022). "SMYD2 also methylates HSP90AB1 at lysines 531 and 574 to accelerate the proliferation of cancer cells." (PMID 31370883, 2019). "However, the roles and mechanisms by which SMYD2 promotes cancer progression remain unknown." (PMID 29487338, 2018).
cancer (continued). "The invalidation of the published roles for MELK, SMYD2 and SMYD3 suggest that a much higher bar must be set for the use of genetic tools in cancer biology." (PMID 29856759, 2018). "qRT-PCR performed to validate the microarray results showed that expression of a number of cancer-related genes, including HAS3, CD44, TP63, and SMYD2, was decreased by siRNAs targeting DLEU1, while expression of CDH1 was increased by DLEU1 knockdown." (PMID 30069008, 2018). "SMYD2 was first identified as one of the SMYD family members and functions as an oncogene, which is highly expressed in various types of human cancer." (PMID 28915556, 2017). "Thus, all of the known SMYD2-generated methylation events may play a role in cancer." (PMID 26988419, 2016). "Thus, SMYD2 may promote cancer by orchestrating a cellular response to stress in cancer cells." (PMID 26988419, 2016). "The lysine methyltransferase SMYD2 is overexpressed in several cancers and regulates oncogenic signaling through histone and non-histone substrates." (PMID 42306568, 2026). "The SMYD2, SET, and MYND domain-containing protein 2, a lysine methyltransferase, is aberrantly dysregulated in different cancer types, inducing several mitogenic signaling pathways by methylating lysine moieties, activating multiple oncogenic and effector proteins." (PMID 40807332, 2025). "The findings suggest that targeting SMYD family members, especially SMYD2 and SMYD3, could be an effective cancer treatment strategy." (PMID 39482529, 2024). "Therefore, SMYD2 plays a crucial role in inducing changes in the epithelial–mesenchymal transition (EMT) and remodeling of the cytoskeleton in cancer metastasis." (PMID 39482529, 2024). "SMYD2 is involved in many different cancers, but its role in NSCLC is not yet completely elucidated." (PMID 37513898, 2023). "A prior study has highlighted that knockout of CRISPR/Cas9 across 313 cell lines shows no proliferative effects, and that SMYD2 is not required for autonomous proliferation of cancer cells." (PMID 35668081, 2022). "In addition, quantitative real-time PCR results showed that the expression levels of ATP1A2, CILP, and THSD4 were downregulated and the expressions of SMYD2 and GAPDHP1 were upregulated in cancer tissues compared with normal tissues." (PMID 35498536, 2022). "Recent evidences, however, show no impact of Smyd2–3 inhibition on cancer cell proliferation in vitro." (PMID 31069954, 2019). "In contrast, LLY-507 displayed anti-proliferative activity against cancer cell lines of all types tested irrespective of SMYD2 expression, with the majority of cells demonstrating anti-proliferative IC50 values between 1 and 5 μM." (PMID 29856759, 2018). "In conclusion, SMYD2 is a KMT that is dispensable for the development of mice and the maintenance of homeostasis in adult mice, including in the pancreas, but whose expression is elevated in PDAC and other cancers." (PMID 26988419, 2016). "Furthermore, SMYD2 reportedly plays an important role in the growth of various cancers through nonhistone methylation." (PMID 39482529, 2024). "However, it was also elaborated that SMYD2 inhibitors showed no impact on the cell proliferation of more than 240 cancer cell lines regardless of genetic or histological background." (PMID 35668081, 2022).
cancer (continued). "Recent reports may also indicate a role for SMYD2 and SMYD3 in the systemic response to cancer." (PMID 29856759, 2018). "However, our data suggests that the methylation of BCAR3 induced by SMYD2 overexpression highjacks the BCAR3-p130Cas regulatory mechanism of cell adhesion and cell protrusion by directly recruiting major actors of lamellipodia maturation, enhancing cancer cells capacity." (PMID 38296970, 2024). "Based on these findings, we conclude that despite previous observations using RNAi based techniques and early stage chemical probes, SMYD2 and SMYD3 are not required for autonomous proliferation of cancer cells." (PMID 29856759, 2018). "The data presented in this work offer strong evidence that in contrast to some of the literature, SMYD2 and SMYD3 are not required for cancer proliferation in vitro." (PMID 29856759, 2018). "Nevertheless, and in contrast to many of the earlier studies summarized above, these SMYD2 and SMYD3 inhibitors show no impact on the cell proliferation of more than 240 cancer cell lines regardless of genetic or histological background." (PMID 29856759, 2018). "Moreover, in cancer-related nonhistone methylation, SMYD2 methylates the RB1, ALK, and β-catenin proteins to regulate the cell cycle and cell proliferation, implying that SMYD2 is a potential therapeutic target for cancer treatment." (PMID 37121971, 2023).